AMBRA1 (autophagy and beclin 1 regulator 1)
Diseases named in the same sentence as AMBRA1 in open-access papers (continued):
Sharing a sentence is not in itself a finding about the gene and the disease.
tumor (continued). "To verify the effect of AMBRA1 and miR‐1178 expression on tumour growth in vivo, we performed xenograft experiments in nude mice." (PMID 40464146, 2025). "A mouse tumour xenograft model was conducted to assess the roles of the AMBRA1‐miR‐1178 axis on NSCLC progression in vivo." (PMID 40464146, 2025). "It has been suggested that AMBRA1 contributes to the proliferation-quiescence decision and tumor suppression." (PMID 40734673, 2025). "Rescue experiment results confirmed that miR‐1178 overexpression partially weakened the suppressive effect of AMBRA1 overexpression on the cell proliferation, invasion, and cycle progression of A549 and H1299 cells, and xenograft tumour growth in vivo." (PMID 40464146, 2025). "AMBRA1 is a substrate receptor of the ubiquitin-conjugating system and serves as a tumor suppressor." (PMID 40734673, 2025). "The development of cellular senescence in AMBRA1-deficient STAD cells is one of our study’s most exciting discoveries; it reveals a novel mechanism by which AMBRA1 promotes tumor progression." (PMID 39720719, 2024). "Previous research has shown that AMBRA1 can function as both a tumor suppressor and an oncogene, depending on the cancer type." (PMID 39720719, 2024). "Together, our data provide evidence that AMBRA1 acts as a context-specific tumor suppressor in ATRT cells, where tumor suppressive activity is associated with negative regulation of mitotic regulators." (PMID 39617889, 2024). "While we provide evidence for a direct regulation of aurora kinases by AMBRA1, the mechanism of cell type-specific tumor suppressive activity of AMBRA1 has still to be elucidated." (PMID 39617889, 2024). "Mechanistically, tumor paracrine TGFβ2 signaling decreases the expression of AMBRA1 in keratinocytes and disrupts epidermal integrity, facilitating tumor ulceration and/or metastasis." (PMID 39201498, 2024). "Surprisingly, our study reveals a very interesting and novel context-specific tumor suppressive activity of the autophagy regulator AMBRA1 in ATRT that depends on the negative regulation of G2/M phase mediators." (PMID 39617889, 2024). "Beyond its effects on individual cellular processes, our findings on AMBRA1’s role in cellular senescence and apoptosis provide crucial insights into its broader function in regulating tumor plasticity in STAD." (PMID 39720719, 2024). "The E3 ligase adaptor, AMBRA1 regulates autophagy and plays a crucial role in tumor initiation and development." (PMID 39720719, 2024). "The result demonstrated that AMBRA1 KO dramatically reduced tumor growth (p < 0.01) and size (p < 0.05)." (PMID 39720719, 2024). "Our findings on AMBRA1’s role in cellular senescence and apoptosis provide crucial insights into its broader function in regulating tumor plasticity in STAD." (PMID 39720719, 2024). "Histological and immunohistochemical analyses of AMBRA1-KO tumor tissues revealed significant alterations in tumor structure and cellular characteristics compared to control tumors." (PMID 39720719, 2024). "This study investigates the role of Autophagy and Beclin 1 Regulator 1 (AMBRA1) in regulating tumor plasticity in STAD progression." (PMID 39720719, 2024). "Subsequently, we investigated the impact of AMBRA1 on the expression of EMT-related markers using immunohistochemistry (IHC) in tumor tissues." (PMID 39720719, 2024). "Future research should focus on elucidating AMBRA1’s influence on various immune cell types, such as T cells and macrophages, and their roles in tumor progression or suppression within the STAD." (PMID 39720719, 2024). "Through in vitro and in vivo studies, we demonstrated that AMBRA1 depletion significantly impairs tumor growth, alters cellular architecture, and increases markers of senescence and DNA damage." (PMID 39720719, 2024).
tumor (continued). "Of note, and given the relevance of TGFβ in regulating Treg cell biology in cancer, AMBRA1 has been shown to increase the Treg response in different pathological conditions, including tumor immunosurveillance and progression." (PMID 37460534, 2023). "In the future, with sufficient time and funding, we will continue to explore how Ambra1 affects cyclin D1 expression, migration, invasion, and apoptosis in tumor cells through autophagy and the molecular mechanism by which Ambra1 regulates cyclin D1." (PMID 37225761, 2023). "As a scaffold protein, AMBRA1 is involved in a wide-range of cellular processes, including the cell cycle, tumor growth and invasion, cell death, and gene expression regulation." (PMID 35875981, 2023). "The aberrant expression and dysregulation of AMBRA1 positively and negatively control tumor formation and progression through diverse signal pathways, such as c-MYC, cyclin D, mTOR, PI3K, STAT3, and TGFβ." (PMID 36237336, 2022). "Radiation therapy is another classical cancer treatment scheme, and AMBRA1 also regulates tumor sensitivity to radiotherapy." (PMID 36237336, 2022). "In turn, does cyclin D mediate all functions of AMBRA1 in tumor suppression and CDK4/6 inhibitor resistance?" (PMID 34413284, 2021). "Recently, AMBRA1 has emerged as a tumor suppressor that mediates the degradation of proto-oncogene c-Myc and D-type cyclins." (PMID 34769507, 2021). "Despite the faster growth kinetics of Ambra1-deficient tumors, the proliferation rate of BPA−/− mice analyzed at the final endpoint (i.e., after 42 days, when maximum tolerated tumor size was reached) appeared slightly, but significantly, decreased." (PMID 33953176, 2021). "The current study provided novel insights into the tumor-suppressive mechanism of AMBRA1 and the post-translational modification of ALDH1B1, a CSC marker." (PMID 34769507, 2021). "The role played by Beclin 1 and Ambra1 as tumour suppressors is also evidenced by the identification of their binding partners, most of which are implicated in tumorigenesis, such as Bcl-2." (PMID 26735341, 2016). "Another protagonist of this signaling pathway involving BCL-2 family members during autophagy is the putative tumor suppressor AMBRA1 (autophagy/beclin-1 regulator 1), which is a crucial factor in regulating autophagy in vertebrates." (PMID 26284195, 2015). "Our study confirmed that Ambra1 is an important factor in the pathways that regulate tumor cell survival in SW620 CRC cells." (PMID 24587252, 2014). "Furthermore, several researches have also shown that AMBRA1 participates in the modulation of tumour cell migration and invasion via epithelial‐mesenchymal transition (EMT)." (PMID 40464146, 2025). "Furthermore, the synergistic tumor suppression of combination treatment also exhibited the same trend with caspase inactivation when performed with Ambra1 overexpression." (PMID 39753527, 2025). "Given the importance of miR-7-5p and AMBRA1 in tumor initiation and development, the current study investigated whether miR-7-5p regulates AMBRA1, and if miR-7-5p is MYC-dependent in DLBCL." (PMID 38393538, 2025). "AMBRA1, which was initially reported to be essential for nervous system development via autophagy and cell proliferation control, also functions as a tumor suppressor by regulating the ubiquitination of D-type cyclins through interaction with DDB1-Cullin4A/4 B E3 ligase." (PMID 40734673, 2025). "Also, the results from the TUNEL assay revealed that miR‐1178‐oe partially inhibited AMBRA1‐oe‐induced tumour cell apoptosis." (PMID 40464146, 2025). "Although we have focused on cyclin D expression in association with S entry in this study, it is plausible that AMBRA1 has other target molecules, as well as autophagy-related molecules, that may play a role in controlling cell proliferation and tumor growth." (PMID 40734673, 2025).
tumor (continued). "Therefore, AMBRA1 participates in tumorigenesis and progression by regulating tumour cell autophagy, apoptosis, cell cycle, proliferation, and metastasis." (PMID 40464146, 2025). "AMBRA1 regulates multiple pathological processes in cancer cells, but the specific role it plays depends on the tumour microenvironment and genetic background, indicating that it can act as an oncogene or a tumour suppressor gene." (PMID 40464146, 2025). "In addition to regulating mitophagy, Ambra1 acts as a tumor suppressor gene in vivo; it inhibits cell cycle progression into the G1-S phase by promoting the degradation of cyclin D." (PMID 40141351, 2025). "Our data highlighted an unanticipated tumor suppressive role of AMBRA1 mediated by the regulation of G2/M phase mediators in combination with D-type cyclins, suggesting that corresponding cells might be particularly dependent on these mitotic regulators." (PMID 39617889, 2024). "This suggests that AMBRA1 may play a crucial role in modulating immune responses, potentially affecting the tumor’s ability to evade immune surveillance." (PMID 39720719, 2024). "Furthermore, high AMBRA1 expression is associated with increased immune infiltration, particularly T cell CD4+ levels, indicating its potential role in modulating the tumor microenvironment." (PMID 39720719, 2024). "Thus, AMBRA1 emerges as a key regulator of tumor plasticity in STAD, orchestrating a delicate balance between proliferation, senescence, and cell death." (PMID 39720719, 2024). "Additionally, we identify a previously unexplored cell type-specific role for the ubiquitin ligase substrate receptor AMBRA1 by acting as a potent tumor suppressor through regulation of factors involved in G2 and M phase progression." (PMID 39617889, 2024). "Furthermore, this study reveals a unique mechanism of cell cycle inhibition as the basis for tumor suppressive functions of AMBRA1." (PMID 39617889, 2024). "Targeting AMBRA1 may induce tumor cell senescence, apoptosis, and potentiate anti-tumor immunity, providing a rationale for developing AMBRA1-targeted precision therapies to improve clinical outcomes in STAD patients." (PMID 39720719, 2024). "Together, these analyses reveal context-specific tumor suppressor activity of AMBRA1 which might be related to descent from the neural crest lineage." (PMID 39617889, 2024). "Mechanistically, we provide evidence for a previously unappreciated context-dependent role of the ubiquitin ligase receptor AMBRA1 in inhibiting cell cycle progression at the level of mitosis that contributes to an understanding of context-specific differences in tumor suppressive activity." (PMID 39617889, 2024). "Our findings suggest a unique tumor suppressor function for Ambra1 in the development of MCL." (PMID 37225761, 2023). "Targeting AMBRA1 expression levels or regulatory interactions could increase the sensitivity of cancer cells to anticancer drugs or inhibit tumorigenesis and tumor progression." (PMID 37993427, 2023). "Thus, this study suggests that AMBRA1 serves as an important tumor suppressor by limiting UVM cell growth." (PMID 34901460, 2022). "AMBRA1 is a key regulator of the autophagy signaling network and a tumor suppressor." (PMID 36232425, 2022). "More recently, the role of AMBRA1 as tumor suppressor has been further extended, as by its regulation of cell cycle by Cyclin D1 stabilization (via interaction with the E3 Ubiquitin ligase DDB1-Cullin4) and of malignant invasiveness (through focal adhesion kinase FAK1 hyperactivation)." (PMID 36243772, 2022). "In sum, analysing different MB cell lines, primary tumour samples, orthotopic xenograft models, and an immunocompetent MBGroup3 mouse model, we demonstrate a novel mechanism of action for AMBRA1 in the control of MBGroup3 oncogenesis through regulation of both STAT3 signalling and autophagy." (PMID 34302498, 2021).
tumor (continued). "Importantly, Ambra1 has been proposed to act as tumor suppressor, since Ambra1 absence and haploinsufficiency, respectively, lead to cellular hyperproliferation and onset of spontaneous tumors in animal models." (PMID 33953176, 2021). "AMBRA1 mutant mice develop spontaneous tumors, suggesting a tumor suppressor role for AMBRA1." (PMID 31121959, 2019). "One study suggested that Ambra1 may have a tumour suppressor role, as it is involved in the degradation of c-Myc induced by dephosphorylation by PP2A, resulting in reduced proliferation and tumourigenesis." (PMID 28362576, 2017). "Moreover, the heterozygous deletion in mice of essential autophagy genes such as Beclin1 and Ambra1 leads to high incidence of spontaneous tumours." (PMID 26735341, 2016). "In the tumor samples, AMBRA1 expression was instead observed in 100 % of cases." (PMID 26423274, 2015). "In addition, in vivo animal studies are essential for exploring the role of Ambra1 in the pro-survival pathways that contribute to CRC tumor growth, survival and chemoresistance." (PMID 24587252, 2014). "Importantly, the pharmacological inhibition of caspases or the Ambra1 overexpression could restore tumor proliferation under the vitamin D and radiation combination treatment." (PMID 39753527, 2025). "Besides, AMBRA1 is the main regulator of D‐type cyclins degradation and an upstream main regulator transitioning from G1 to S phase; therefore, it is a participant in regulating cell cycle in tumour cells." (PMID 40464146, 2025). "However, other genes with similar tumor suppressive function in our screen, such as Ambra1, Gpatch8, and Spred1, may be less appreciated as tumor suppressors." (PMID 38302473, 2024). "Thus, AMBRA1 serves as an important tumor suppressor by limiting tumor growth." (PMID 34901460, 2022). "Remarkably, the kinetics of tumor growth was dramatically reduced upon FAKi administration in sBPA−/− mice, as also demonstrated by reduced tumor weight at the time of collection, underlining the key role of the FAK1 signaling axis in sustaining Ambra1-deficient tumors." (PMID 33953176, 2021). "Notably, AMBRA1 may also influence cancer metabolism and tumor progression by regulating the degradation of c-Myc." (PMID 31121959, 2019). "In our study, AMBRA1 overexpression suppressed NSCLC cell proliferation and invasion, as well as in vivo NSCLC tumour growth, which was consistent with previous research." (PMID 40464146, 2025). "AMBRA1 overexpression suppressed NSCLC cell proliferation and invasion, while promoting apoptosis and G0/G1 phase cell cycle arrest in vitro, and inhibited tumour growth in vivo." (PMID 40464146, 2025). "In conclusion, our study reveals AMBRA1 as a critical oncogenic driver in STAD, regulating tumor plasticity, proliferation, and resistance to cellular senescence and apoptosis." (PMID 39720719, 2024). "AMBRA1 binds CUL4-DDB1 complex and targets D-type cyclins for ubiquitin-mediated degradation, thus acting as a tumor suppressor and assuring normal cell cycle progression." (PMID 37106439, 2023). "A detailed picture of the mechanism by which AMBRA1 engages CRL4 is needed to provide new insight into AMBRA1 regulation, the relationship between autophagy, the UPS pathway and tumor growth, and for the development of novel therapeutics." (PMID 37993427, 2023). "The study finally identified that AMBRA1 interacts with the phosphatase PP2A and enhances its phosphatase activity on the proto-oncogene c-MYC, which further prevents tumorigenesis and tumor hyperproliferation." (PMID 36237336, 2022). "AMBRA1-deficiency leads to uncontrolled cell proliferation as well, and AMBRA1 can also interact with BECN1, again supporting a tumor-suppressive function of autophagy." (PMID 31671879, 2019). "Therefore, AMBRA1 decreased CDK2 expression by inhibiting miR‐1178 expression, which ultimately suppressed tumour growth and metastasis of NSCLC." (PMID 40464146, 2025).
tumor (continued). "Compared with normal tissues, tumor tissues showed significantly higher mRNA levels of the following key autophagy genes: ATG5, ATG7, ATG3, ATG9A, ATG9B, ATG12, AMBRA1, and NBR1." (PMID 32582551, 2020). "Moreover, the HPV16 E7 protein has been reported to induce the degradation of not only the key autophagy initiator protein AMBRA1, but also STING, which may promote tumor immune evasion despite a putative higher abundance of TILs in HPV16+ HNSCC." (PMID 38291202, 2024). "The observed effects of Rapamycin on tumor suppression are likely to involve the autophagy process, evidenced by the inhibition of autophagy modulators (TGFβ1, RGS19 and AKT1), autophagosome biogenesis components (AMBRA1, ATG9B and TMEM74) and autophagy byproducts (APP)." (PMID 38276004, 2024). "In addition, how Ambra1 affects cyclin D1 expression, migration, invasion, and apoptosis in tumor cells through autophagy and the molecular mechanism by which Ambra1 regulates cyclin D1 expression are not clear." (PMID 37225761, 2023). "The increases observed in the mRNA and protein levels of LC8-2 induced by Amblyomin-X in tumor cells together with the decreased expression of AMBRA1 and its co-localization with dynein chains only in MIA PaCa-2 cells suggest that AMBRA1 could be sequestered to LC8-2 to become inactive." (PMID 25479096, 2014). "Additionally, Amblyomin-X increased the expression of various chains of the molecular motor dynein in tumor cells, modulated specific ubiquitin linkage signaling and inhibited autophagy activation by modulating mTOR, LC3 and AMBRA1 with probable dynein involvement." (PMID 25479096, 2014). "Although AMBRA1, ATG9B and TMEM74 suppression by Rapamycin signals defects in autophagy, evidence suggests the existence of a self-regulatory loop directing tumor cells to death rather than autophagy." (PMID 38276004, 2024).